MATN3 (matrilin 3)
Diseases named in the same sentence as MATN3 in open-access papers (continued):
Sharing a sentence is not in itself a finding about the gene and the disease.
chondrodysplasia (12 papers, 2008 to 2025). "Related to collagen structure is the complex formed between DCN and matrilin-1, a protein involved in matrix assembly, whose relative, matrilin-3, has been linked to certain chondrodysplasias." (PMID 40001470, 2025). "We demonstrate here for the first time that MED or SEMD chondrodysplasia associated MATN3 missense mutations have a dominant effect to render attenuated chondrogenesis and premature hypertrophy in chondroprogenitor cells." (PMID 25196597, 2014). "Studies to analyze the underlying mechanisms of chondrodysplasia have previously focused on the effects of the MATN3 missense mutations on chondrocytes." (PMID 25196597, 2014). "Mutations in human MATN3 are associated with a variety of human cartilage degenerative diseases including chondrodysplasia and OA." (PMID 22967398, 2012). "Although matrilin-3 is the only matrilin family member that has been associated with chondrodysplasia so far, more and more point mutations within the vWF A domain of matrilin-3 have been reported to cause MED." (PMID 18518980, 2008). "In humans, dominant-negative mutations in MATN3 lead to various forms of mild chondrodysplasias." (PMID 31963938, 2020). "We hypothesized that deletion of matrilin 1, which would abolish the formation of matrilin 1/matrilin 3 heterotetramers, would also eliminate the secretion of mutant matrilin 3 into the ECM and increase the severity of chondrodysplasia in mice with the Matn3 V194D mutation." (PMID 22083516, 2012). "Several chondrodysplasia mutations including MED and SEMD have been mapped to MATN3, a gene encoding a non-collagenous matrix glycoprotein." (PMID 25196597, 2014). "The structural and/or functional effect of this mutant matrilin 3 in the ECM is not known, nor is the extent to which its presence in the ECM might contribute to the chondrodysplasia phenotype." (PMID 22083516, 2012).
gastric cancer (8 papers, 2020 to 2025). A primary or metastatic malignant neoplasm involving the stomach. "The three genes used to assess GPSGC risk scores in our study (VCAN, CLIP4 and MATN3) have been previously reported to be associated with gastric cancer." (PMID 32754268, 2020). "Overall, our data indicated that MATN3 may have a diagnostic and prognostic value for patients with advanced gastric cancer and assist to improve clinical outcomes for GC patients." (PMID 34900024, 2021). "MATN3 was aberrantly methylated and dysregulated in gastric cancer and related to an undesirable prognosis." (PMID 34746312, 2021). "Contrary to the results of this study, increased expression of four genes (CLIP4, NOX4, LAMP5, and MATN3) is related to poor prognosis, and the expression of these genes is higher in stromal components than in epithelial cancer cells in gastric cancer." (PMID 33575272, 2020). "Here, we developed an EMT-related RS model that was comprised of SERPINE1, PCOLCE2, MATN3, and DKK1 in gastric cancer via the LASSO method, which may classify gastric cancer patients into the high- and low-risk categories." (PMID 34746312, 2021).
pseudoachondroplasia (7 papers, 2010 to 2022). Pseudoachondroplasia is characterized by severe growth deficiency and deformations such as bow legs and hyperlordosis. "In MED cases, the mutations are either on the COMP or MATN3 gene, the former also being known to cause pseudoachondroplasia (PSACH), another disease in which windswept deformity can be found." (PMID 35626880, 2022).
breast carcinoma (4 papers, 2020 to 2024). "Moreover, poor OS in patients with breast cancer was significantly associated with the concurrent downregulation of HOXB2, MATN3, and ECM2." (PMID 38322121, 2024). "As HOXB2, MATN3, and ECM2 expressions positively correlated in breast cancer cells, we re-analyzed data from patient samples in publicly available clinical datasets of GSE65194 and GSE58812." (PMID 38322121, 2024). "To further confirm the therapeutic efficacy of HOXB2/MATN3 or HOXB2/ECM2 transcriptional axis, we performed IHC for HOXB2, MATN3, and ECM2 in-house with 100 human tissue samples of patients with breast cancer." (PMID 38322121, 2024). "Both MATN3 and ECM2 expressions were positively correlated with HOXB2 expression in the human breast cancer tissues." (PMID 38322121, 2024). "Three of the top four genes enriched in PRC2+-CGI EMT pathway had not been functionally implicated in the EMT phenotype in breast cancer (SERPINE2, DKK1, MATN3)." (PMID 33931649, 2021). "Knockdown of other upregulated ABC genes including PRR13, EGLN3, HSD11B2, and MATN3 also inhibited the proliferation of various breast cancer cell lines (data not shown)." (PMID 32539762, 2020).
spondyloepimetaphyseal dysplasia (4 papers, 2005 to 2020). An osteochondrodysplasia that results in abnormalities of bone growth in the vertebral column, epiphysis, and metaphysis. "As in the case of spondyloepimetaphyseal dysplasia (SEMD) and multiple epiphyseal dysplasias (MEDs), mutations in the matrilin-3 gene cause an aberrant response towards TGF-β and the differentiation of ATDC5 chondroprogenitor cells." (PMID 33255398, 2020).
Epiphyseal dysplasia (3 papers, 2005 to 2021). "Indeed, mutations in the genes encoding COMP and matrilin-3 result in multiple epiphyseal dysplasias." (PMID 24886698, 2014).
hepatocellular carcinoma (3 papers, 2024 to 2025). A malignant tumor that arises from hepatocytes. "We performed immunohistochemistry on hepatocellular carcinoma as a means of confirming MATN3 expression in tumor tissue and normal tissue samples." (PMID 39991588, 2025). "The findings indicated that MATN3 protein was significantly overexpressed in hepatocellular carcinoma tissues compared to normal liver tissues, and the difference in immunohistochemical staining scores between hepatocellular carcinoma tissues and normal liver tissues was statistically significant." (PMID 39991588, 2025). "In this study, the selection of MATN3 as a target was guided by our RNA sequencing data, which identified MATN3 as one of the most significantly downregulated genes after α-Pinene treatment in hepatocellular carcinoma cell line." (PMID 41004439, 2025). "In vitro experiments in hepatocellular carcinoma have verified that MATN3 knockdown can inhibit the proliferation and migration of hepatocellular carcinoma, but the specific regulatory mechanism of MATN3 in hepatocellular carcinoma remains to be further studied." (PMID 39991588, 2025). "The same trend of worse prognosis was observed in patients with lung cancer, renal clear cell carcinoma, or hepatocellular carcinoma exhibiting low HOXB2 and/or low HOXB2/MATN3/ECM2 expression." (PMID 38322121, 2024).
gastric adenocarcinoma (2 papers, 2021 to 2022). "It was verified that MATN3 protein was upregulated in gastric adenocarcinoma, acting as a predictor of poor prognosis." (PMID 34249086, 2021). "Some studies have shown that MATN3 and AMIGO2 are overexpressed in gastric adenocarcinoma and can serve as markers of poor prognosis." (PMID 35719914, 2022).
Hip dysplasia (2 papers, 2012 to 2014). The presence of developmental dysplasia of the hip. "In comparison between MATN-3 and COMP-MED, the COMP-MED patients were shorter in height, and had more gait abnormality and hip dysplasia, while the MATN3-MED patients had a relatively milder phenotype from an orthopaedic point of view." (PMID 24629099, 2014).
liver cancer (2 papers, 2025). An epithelial or non-epithelial malignant neoplasm that arises from the liver. "Knocking down MATN3 in liver cancer cell lines verified that MATN3 can reduce the proliferation and migration ability of liver cancer cells, which provided a certain basis for further exploration of the effects of MATN3 on cancer." (PMID 39991588, 2025). "Notably, MATN3 expression was almost undetectable in hematological malignancies’ cell lines, Conversely, liver cancer cell lines exhibited the highest levels of MATN3 expression." (PMID 41004439, 2025). "In addition, we also knocked down MATN3 in liver cancer cell lines Huh7 and Hep3B to study the effect of MATN3 on the function of liver cancer cells." (PMID 39991588, 2025).
bladder cancer (1 paper, 2025). "In contrast, other cancers like bladder cancer and liver hepatocellular carcinoma show instances of heterozygous amplification, potentially correlating with the higher expression levels and the poorer prognosis associated with MATN3 in these conditions." (PMID 41004439, 2025).
cartilage disease (1 paper, 2008). Softening and degeneration of the CARTILAGE. "This may explain how different mutations within matrilin-3 lead to a variety of cartilage diseases." (PMID 18518980, 2008).
chordoma (1 paper, 2022). Chordomas are rare malignant tumors arising from embryonic remnants of the notochord in axial skeleton. "As expected, stroma-rich chordomas showed elevated expression of cartilage-associated genes, including COMP, MATN3, and COL11A226,27." (PMID 36192442, 2022).
clubfoot (1 paper, 2023). The most common congenital deformation of the foot, occurring in 1 of 1,000 live births. "Mutations in genes encoding the ECM proteins COL9A1, COL9A2, COL9A3, COMP and MATN3, as well as the transmembrane glycoprotein involved in matrix organization, SLC26A2, have been associated with clubfoot." (PMID 37964341, 2023).
COVID-19 (1 paper, 2022). A disease caused by infection with severe acute respiratory syndrome coronavirus 2. "Although recent literature data confirms the association of MATN3 with COVID-19 severity, its pathophysiological role is not clear." (PMID 36012423, 2022).
disc degeneration (1 paper, 2020). "T2-weighted MRI and histological analyses demonstrated that matrilin-3-primed Ad-MSCs suppressed the acute phase of disc degeneration in the rabbit model." (PMID 32831130, 2020). "Finally, we investigated whether matrilin-3-primed Ad-MSCs could improve Ad-MSC function and enhance the regenerative effect in a rabbit model of disc degeneration." (PMID 32831130, 2020).
dwarfism (1 paper, 2015). "However, such comparisons demonstrate that based on bone growth, the ColIITgcog mouse dwarfism is milder than that seen in the Matn3 p.V194D and ColIITgrwd mice but apparently greater than that seen in the COMP p.T583M mouse at 3 weeks of age." (PMID 25693198, 2015).
intervertebral disc degeneration (1 paper, 2021). "Our study suggests that reduced MATN3 can be considered a characteristic of intervertebral disc degeneration." (PMID 34136064, 2021). "Moreover, the role and mechanism of MATN3 in the treatment of intervertebral disc degeneration by USC-exos were verified, with the therapeutic effect achieved by regulating the TGF-β content." (PMID 34136064, 2021). "Collectively, the radiographic results and morphological analyses indicated that full-ingredient USC-exos with MATN3 could significantly ameliorate intervertebral disc degeneration, while the beneficial effect was attenuated when MATN3 was knocked down in USC-exos." (PMID 34136064, 2021). "USC-exos were found to be rich in MATN3 protein, and exosomal MATN3 was required for USC-exos-induced promotion of NPC proliferation and ECM synthesis, as well as alleviation of intervertebral disc degeneration in IVD rats." (PMID 34136064, 2021). "The presence of MATN3 in USC-exos was verified in subsequent experiments, suggesting that USC-exos may inhibit intervertebral disc degeneration through MATN3." (PMID 34136064, 2021). "USC-exos may represent a potentially effective agent for alleviating intervertebral disc degeneration by promoting NPC proliferation and ECM synthesis by transferring the MATN3 protein." (PMID 34136064, 2021).
lumbar disc degeneration (1 paper, 2023). "In a rabbit model of lumbar disc degeneration, these matrilin-3-primed ASC spheroids led to improved tissue restoration." (PMID 38069151, 2023).
metastatic tumors (1 paper, 2024). "In particular, the expression of HOXB2, MATN3, and ECM2 was significantly suppressed in metastatic tumors compared to that in primary tumors." (PMID 38322121, 2024).
ovarian carcinoma (1 paper, 2025). A malignant neoplasm originating from the surface ovarian epithelium. "Cancers such as ovarian cancer and kidney chromophobe exhibit significant rates of homozygous deletions, which might contribute to lower MATN3 expression levels observed in these cancers, as previously discussed." (PMID 41004439, 2025).
pancreatic cancer (1 paper, 2020). "CLUSTER1 also included up-regulated genes with unknown importance in pancreatic cancer, such as MATN3, SERPINA1, and IGFBP5." (PMID 33194391, 2020).
pneumonitis (1 paper, 2022). An inflammatory process affecting the lung parenchyma. "Several of these filtered candidates were found to be secreted (C12orf49, COL10A1, FNDC4, ITLN2, MATN3, PDZD2, RS1, SCRG1, and ST6GALNAC5) making them potential candidate biomarkers useful for distinguishing IPF from pneumonitis." (PMID 35628257, 2022).
short-limbed dwarfism (1 paper, 2023). "Autosomal dominant mutations in the MATN3 gene, encoding the cartilage extracellular matrix protein matrilin-3, have been shown to cause the short-limbed dwarfism multiple epiphyseal dysplasia (MED) type 5 (EDM5; OMIM #607078)." (PMID 36675026, 2023).
tumor (16 papers, 2020 to 2026). "This transition was prompted by the need to understand whether the observed downregulation of MATN3 could be linked to general mechanisms of tumorigenesis and tumor progression in diverse cancer types." (PMID 41004439, 2025). "Our comprehensive examination of MATN3 has extended into the study of its mutational landscape across multiple cancer types, offering insights into its genetic alterations and the implications for tumor behavior and therapy response." (PMID 41004439, 2025). "The comprehensive analysis of MATN3 mutations and their correlation with various indicators of tumor heterogeneity offers insights into the complex role this gene may play across different cancer types." (PMID 41004439, 2025). "After establishing a connection between MATN3 mutations and tumor heterogeneity, further analysis was conducted to examine the relationship between MATN3 and tumor immune infiltration across different cancer types using algorithms such as EPIC, ESTIMATE, and TIMER." (PMID 41004439, 2025). "Notably, our research has elucidated a significant positive correlation between MATN3 expression and cancer-associated fibroblasts, a pattern that is consistently observed across a majority of tumor types." (PMID 41004439, 2025). "Higher levels of MATN3 were associated with advanced tumor stages and positive cancer status." (PMID 34900024, 2021). "Furthermore, the correlation between MATN3 expression and indicators of tumor heterogeneity, such as tumor purity, tumor mutational burden, microsatellite instability, and homologous recombination deficiency, suggested a complex interplay between MATN3 and the tumor microenvironment." (PMID 41004439, 2025). "This relationship suggests a potential role for MATN3 in modulating the tumor stroma and influencing processes like angiogenesis and tumor-stromal crosstalk." (PMID 41004439, 2025). "Conversely, in ACC, SKCM, TGCT, and THYM, MATN3 expression is significantly positively correlated with tumor purity." (PMID 41004439, 2025). "These pathways are fundamentally involved in regulating cell proliferation, survival, and differentiation, highlighting the potential multifaceted role of MATN3 in tumor biology and cellular behavior." (PMID 41004439, 2025). "The protein-protein interaction network and Gene Ontology analyses further reinforced the potential involvement of MATN3 in extracellular mechanisms and cell communication, underscoring its multifaceted roles in the tumor microenvironment." (PMID 41004439, 2025). "Further exploration revealed a strong correlation between MATN3 expression and immune infiltration, as well as significant associations with key immunomodulatory genes, suggesting an intricate role of MATN3 in the tumor immune environment." (PMID 41004439, 2025). "These pathways suggest a mechanistic link between MATN3 expression and the cellular dynamics that facilitate tumor cell migration and adhesion." (PMID 41004439, 2025). "In the study of tumor purity, MATN3 expression shows a varying relationship depending on the cancer type." (PMID 41004439, 2025). "Previous results have established a correlation between MATN3 and tumor purity, which is influenced by immune cell infiltration and the tumor microenvironment." (PMID 41004439, 2025). "We observed that MATN3 expression at the promoter methylation level was higher in tumor tissues of KIRP, LUAD, and LUSC than in normal tissues of these cancer types, and was opposite in BLCA, LIHC, PCPG, STAD, TGCT, and UCEC." (PMID 39991588, 2025). "The correlation between MATN3 and various tumor microenvironment cells was calculated using the EPIC algorithm." (PMID 41004439, 2025). "Conversely, upregulation of E2F targets (e.g., PRDX4, MCM2; FDR = 2.6e-24) and extracellular matrix genes (e.g., COCH, MATN3; FDR = 8.0e-18) were strongly associated with tumor growth and resistance to ICI-4W." (PMID 37433281, 2023).